FAM72C (family with sequence similarity 72 member C)
Synonyms: RP5-998N21.9
Tractability: Antibody: the Human Protein Atlas places it where antibodies can reach. PROTAC: ubiquitination databases record sites on it.
Gene: Protein-coding gene on chromosome 1 (143,955,287 to 143,971,986, reverse strand). Ensembl gene ENSG00000263513.
Subcellular location (Human Protein Atlas): Vesicles; Cytosol; Plasma membrane
Gene Ontology:
Cellular component: cytosol
Genetic constraint (gnomAD): Loss-of-function variants: 1 observed, 1.79 expected, observed/expected ratio (o/e) 0.56, 90% interval 0.18 to 1.79. That is too few expected variants to judge how well the gene tolerates losing a copy. Missense variants: 3 observed, 24.51 expected, observed/expected ratio (o/e) 0.12, 90% interval 0.055 to 0.32. Synonymous variants: 0 observed, 6.58 expected, observed/expected ratio (o/e) 0, 90% interval 0 to 0.46.
Homologues: Orthologues: chimpanzee FAM72A (98% identical), macaque FAM72A (98% identical), guinea pig Fam72a (91% identical), mouse Fam72a (88% identical), rat Fam72a (88% identical), dog FAM72A (77% identical), zebrafish FAM72A (61% identical), tropical clawed frog fam72a (52% identical). Paralogues in human: FAM72D (99% identical), FAM72A (98% identical), FAM72B (97% identical).
Diseases named in the same sentence as FAM72C in open-access papers:
FAM72C is named in the same sentence as 3 diseases in open-access papers, as found by Europe PMC text mining. Sharing a sentence is not in itself a finding about the gene and the disease. The quoted sentences say what the papers report.
breast carcinoma (1 paper, 2025). "Our data show that the expression levels of all FAM72 paralogues, with the exception of FAM72C, were increased in both colon and breast cancer tissues relative to the normal flanking tissues." (PMID 40604025, 2025).
systemic lupus erythematosus (1 paper, 2025). An autoimmune multi-organ disease typically associated with vasculopathy and autoantibody production. "In disease-associated studies, FAM72C has been identified as a potential therapeutic target in systemic lupus erythematosus (SLE) through Bayesian gene network analysis." (PMID 41153357, 2025).
FAM72C also shares sentences with these, for which no sentence is quoted: cancer (1 paper).